CMAHP (cytidine monophospho-N-acetylneuraminic acid hydroxylase, pseudogene)
Description:
Sialic acids are components of carbohydrate chains of glycoconjugates and are involved in cell-cell recognition and cell-pathogen interactions. That protein has no CMP-N-acetylneuraminate monooxygenase activity and is not able to convert CMP-N-acetylneuraminic acid (CMP-Neu5Ac) into its hydroxylated derivative CMP-N-glycolylneuraminic acid (CMP-Neu5Gc), a sialic acid abundantly expressed at the surface of many cells in vertebrates. However, it may play a role in Wnt signaling.
Synonyms: formerly CMAH
Gene: Transcribed unitary pseudogene on chromosome 6 (25,081,862 to 25,138,081, reverse strand). Ensembl gene ENSG00000168405.
Subcellular location: Cytoplasm
Diseases named in the same sentence as CMAHP in open-access papers:
CMAHP is named in the same sentence as 7 diseases in open-access papers, as found by Europe PMC text mining. Sharing a sentence is not in itself a finding about the gene and the disease. The quoted sentences say what the papers report.
gastric cancer (2 papers, 2022 to 2023). A primary or metastatic malignant neoplasm involving the stomach. "Similarly, CMAHP promotes gastric cancer metastasis formation by reducing the ubiquitination of Snail." (PMID 36348434, 2022).
clear cell renal cell carcinoma (1 paper, 2021). "Different from CMAHP, higher expression of unitary pseudogene CPHL1P was associated with worse patient OS (log-rank test, p = 4.98 × 10-6) in clear cell renal cell carcinoma (KIRC) and worse patient RFS (log-rank test, p = 0.00245) in prostate cancer (PRAD), respectively." (PMID 34425866, 2021).
cutaneous melanoma (1 paper, 2021). A primary melanoma arising from atypical melanocytes in the skin. "Higher CMAHP expression was associated with better patient OS in lung adenocarcinoma (LUAD, log-rank test, p = 0.00142)) and cutaneous melanoma (SKCM, log-rank test, p = 7.47 × 10−6), respectively." (PMID 34425866, 2021).
leukemia (1 paper, 2020). A malignant (clonal) hematologic disorder, involving hematopoietic stem cells and characterized by the presence of primitive or atypical myeloid or lymphoid cells in the bone marrow and the blood. "Among them, only CMAHP was reported to be related to MLL-positive AML, and other lncRNAs have not been reported in leukemia." (PMID 32850463, 2020).
tumor (1 paper, 2023). "RT‐qPCR results revealed that the tumor tissues exhibited significantly higher CMAHP mRNA expression than the normal tissues (P < .01)." (PMID 37265054, 2023). "The CMAHP mRNA expression in the anti‐NeuGc Ab‐positive group was also significantly higher in the tumor tissues than in the normal tissues." (PMID 37265054, 2023). "To address this possibility, we evaluated CMAHP mRNA expression normalized against β‐actin in the normal and tumor portions of the resected liver tissues from the hepatectomized HCC patients (n = 100)." (PMID 37265054, 2023). "CMAHP mRNA expression was significantly higher in the tumor tissues of the NeuGc Ag‐positive group than in the normal tissues (P < .05)." (PMID 37265054, 2023). "The NeuGc Ag‐positive group exhibited a significantly higher CMAHP mRNA expression in the tumor tissues than that in the normal tissues (P < .05)." (PMID 37265054, 2023).
CMAHP also shares sentences with these, for which no sentence is quoted: lung adenocarcinoma (1 paper); prostate carcinoma (1).